CYP2W1 (cytochrome P450 family 2 subfamily W member 1)
Diseases named in the same sentence as CYP2W1 in open-access papers (continued):
Sharing a sentence is not in itself a finding about the gene and the disease.
tumor (continued). "In CRC models, the predominant expression of CYP2W1, CYP2S1, CYP1B1, and CYP2J2 suggests their potential functional involvement in tumour metabolism, xenobiotic processing and disease progression." (PMID 41174467, 2025). "These strategies can be initiated with other P450s that have been identified in tumor cells, such as CYP2J2, CYP2W1, and CYP4Z1." (PMID 31998435, 2020). "In mice‐bearing 5F 203‐sensitive MKN‐45 and 5F 203‐insensitive BGC‐823 tumours in opposite flanks, CYP1A1, CYP2W1 and γH2AX protein in MKN‐45 tumours only following treatment of mice with 5F 203 (5 mg/kg) revealed PD biomarkers of sensitivity." (PMID 31876059, 2020). "Significant induction of CYP1A1 and CYP2W1 protein and mRNA expressions was demonstrated in homogenates of MKN‐45 tumours 24 hours after treatment of mice with 5F 203 (5 mg/kg, ip)." (PMID 31876059, 2020). "In the present study, we compared the pattern expression of CYP1A1, CYP1A2, CYP1B1, CYP2E1, CYP2W1, CYP3A4 and CYP3A5 in paired tumor and normal tissue of child patients with RMS." (PMID 24699256, 2014). "As it has been demonstrated that CYP2W1 is able to activate a variety of chemical carcinogens to genotoxic compounds, CYP2W1 has become a promising tool in targeted therapy for malignancies expressing this enzyme, as it may allow to specifically targeting tumor cells with limited systemic toxicity." (PMID 25144458, 2014). "Using real time quantitative RT-PCR, the gene expression pattern of CYP1A1, CYP1A2, CYP1B1, CYP2E1, CYP2W1, CYP3A4, and CYP3A5 were analyzed in tumor and adjacent non-tumor tissues from 13 child RMS patients." (PMID 24699256, 2014). "Neither CYP1A1 nor CYP2W1 protein was detected in homogenates of MKN‐45 tumours recovered from vehicle‐treated mice." (PMID 31876059, 2020). "In fact, we already demonstrated that CYP2W1 is highly expressed in ACC at both RNA and protein levels, and it could be locally (at tumor level) involved in mitotane metabolism, thus impacting the achievement of the target range." (PMID 32033200, 2020). "This confirms that significant expression of CYP2W1 protein was present in only one tumor sample, and that all other samples lacked detectable expression of this enzyme." (PMID 27598485, 2016). "The expression of CYP2W1 in ACC makes this enzyme a promising drug target, by taking advantage of its ability to convert nontoxic prodrugs (i.e. duocarmicyn precursors) into highly potent tumor toxins." (PMID 25144458, 2014). "Thus, the aim of the present study was to determine the mRNA expression pattern of seven representative CYPs (e.g., CYP1A1, CYP1A2, CYP1B1, CYP2E1, CYP2W1, CYP3A4, and CYP3A5) in paired tumor and normal tissue of childhood patients with RMS." (PMID 24699256, 2014). "CYP2W1 mRNA was expressed in one matched tumor and normal tissue (patient 1), while in other 7 patients (2, 5, 6, 10, 11, 12 and 13) CYP2W1 mRNA was detected in tumor samples but not in their matched normal adjacent samples." (PMID 24699256, 2014). "The overexpression of CYP2W1, CYP3A4 and CYP3A5 in tumor tissues suggests that they may be involved in RMS chemoresistance; furthermore, they may be exploited for the localized activation of anticancer prodrugs." (PMID 24699256, 2014). "However, our study did not investigate the molecular mechanisms driving CYP2W1 activation in tumor tissues." (PMID 40136335, 2025). "Corresponding CYP2W1 protein was detected in 40.5% of tumor samples, while all matched normal tissues lacked detectable expression, suggesting selective activation of this enzyme in a significant subset of pediatric STSs and reinforcing its potential as a targeted therapeutic candidate." (PMID 40136335, 2025). "Finally, the oncogenic RET kinase as well as CYP2W1 are direct PLAGL1/2 targets and may be potential drug targets in this tumor type, which should be top priorities for future functional validation." (PMID 36437415, 2023).
tumor (continued). "Likewise, in the frozen tissue samples the majority of normal tissue (80%) displayed no CYP2W1 expression while the primary tumours from the same source consistently showed high expression." (PMID 34556703, 2021). "Of particular interest is the observation of a bystander effect affecting adjacent cells not expressing CYP2W1 by the toxins generated in CYP2W1 expressing cells, suggesting a relevant therapeutic potential of an anti-tumor strategy exploiting bioactivation by CYP2W1." (PMID 25144458, 2014). "In fact, the activation of an inactive prodrug by CYP2W1 generates an active product that could induce tumor- specific killing, while leaving the surrounding normal, non-CYP2W1 expressing cells unscathed." (PMID 24699256, 2014). "In addition, mRNA isolated from tissues contains a mixture of tumour, stromal, and immune cells, which may result in dilution effects as opposed to IHC, wherein CYP2S1 and CYP2W1 protein expression was assessed only in tumour cells." (PMID 35902379, 2022).
cancer (17 papers, 2014 to 2025). A tumor composed of atypical neoplastic, often pleomorphic cells that invade other tissues. "CYP2S1 and CYP2W1 mRNAs were also associated with luminal A cancers in the METABRIC cohort, all of which are consistent with the reported role of CYP enzymes in the metabolism and oxidation of estrogens." (PMID 35902379, 2022). "Expression of CYP2W1 in any normal tissue carries the risk of toxic side effects of CYP2W1-targeted cancer therapy." (PMID 27598485, 2016). "The involvement of CYP2W1 in the metabolism and oxidation of estrogen, along with the strong association of cytoplasmic CYP2S1 and nuclear CYP2W1 protein with ER‐positive cancers, suggests that these enzymes may be important as prognostic markers in ER‐positive disease." (PMID 35902379, 2022). "The development of CYP2W1-focused therapies, including prodrugs and immunotherapy, is essential to address the unmet clinical needs of this aggressive cancer." (PMID 40136335, 2025). "Integrating CYP2W1-prodrug activation with immunotherapy positions CYP2W1 as a key player in precision oncology, providing safer and more effective therapeutic options for cancer patients." (PMID 40136335, 2025). "The fact that CYP2W1 is aberrantly overexpressed in a significant subset of primary STS tissues but is found absent in normal tissues makes it a promising therapeutic target for the treatment of cancers expressing CYP2W1." (PMID 40136335, 2025). "CYP2W1 is expressed in a cancer-specific way and converts pro-dugs as well as fatty acids like arachidonic acid." (PMID 36744208, 2022). "The CRC specific expression of CYP2W1 and its effective activation of prodrugs makes it a valuable target for novel cancer therapeutics." (PMID 33659048, 2021). "Larger scale clinical studies will be required to validate the potential application of CYP2W1 as a prognostic cancer biomarker." (PMID 33659048, 2021). "Due to its selective expression, CYP2W1 is suggested as a potential prognostic biomarker in hepatocellular and other carcinomas." (PMID 29342849, 2018). "Increased expression of CYP2W1 can be beneficial for the specific prodrug based treatment of cancer (see Introduction)." (PMID 25844926, 2015). "This implies interesting parallels between the developmental and cancer regulatory mechanisms of CYP2W1 expression that were also found to overlap in many oncofetal genes." (PMID 25844926, 2015). "Of major interest is that high CYP2W1 expression is supposed to be restricted to foetal tissues and to some cancers." (PMID 25144458, 2014). "Only CYP2E1 and CYP2W1 mRNA levels in cancer cases were significantly higher compared to normal matched samples (medians: 1.42 versus 1.29, P = 0.028, and 1.53 versus 0, P = 0.012, Wilcoxon rank-sum test, respectively)." (PMID 24699256, 2014). "Motivated by these findings and the therapeutic potential of CYP2W1 in cancer, this study aims to comprehensively investigate CYP2W1 expression across major STS subtypes affecting children and adolescents, evaluating its clinical relevance and prognostic value." (PMID 40136335, 2025). "For instance, CYP2J2 and CYP2W1 were both found to have a higher level of expression in carcinoma cells and transformed tissues where they could have a role in the progression or treatment of cancers." (PMID 31258835, 2019). "The HCC2998 cell model was successfully used to test whether the CYP2W1 expression can be exogenously induced, which might be useful for augmenting the effects of CYP2W1-dependent cancer therapy." (PMID 25844926, 2015). "Taken together, these features make CYP2W1 a potential tool for cancer therapy, as it may activate specific prodrugs into toxic compounds selectively in cancer cells." (PMID 25144458, 2014). "Oxidation by CYP2W1 might contribute to the activation of mitotane and at least in part explain its specific activity in malignancies of the adrenal cortex." (PMID 25144458, 2014).
cancer (continued). "However, the precise molecular mechanisms driving CYP2W1 dysregulation in human cancers remain unclear." (PMID 40136335, 2025). "In addition, screening of a broad spectrum of biologically active molecules yielded a list of potential CYP2W1 inducers that might be instrumental for its up-regulation in cancer tissues, increasing thus the efficacy of prodrug therapy." (PMID 25844926, 2015). "CYP2W1 expression is absent in normal tissue and elevated in several cancer types, including colorectal cancer, thereby providing a potential target for local drug activation in cancer tissues." (PMID 38473371, 2024).
CYP2W1 also shares sentences with these, for which no sentence is quoted: adrenal cancers (1 paper); CNS embryonal tumor (1); head and neck cancer (1); head and neck squamous cell carcinoma (1); metastatic disease (1); ovarian carcinoma (1).